EGFR (epidermal growth factor receptor)
Diseases named in the same sentence as EGFR in open-access papers (continued):
Sharing a sentence is not in itself a finding about the gene and the disease.
tumor (continued). "Therefore, gefitinib, as one of the first-generation EGFR inhibitors, shows better efficacy against tumor cells with high EGFR expression and has higher specificity for cancer cells than for normal cells." (PMID 39926646, 2025). "TD-19 and afatinib induce apoptosis and tumor suppression in EGFR wild-type or mutation-negative NSCLC through CIP2A inhibition, with afatinib also blocking ELK-1-mediated CIP2A transcription." (PMID 40943297, 2025). "It enhances tumor cell growth and survival by regulating endoplasmic reticulum stress and protein folding homeostasis, and it promotes invasion and metastasis through activation of the EGFR signaling pathway." (PMID 39990664, 2025). "Liver biopsy confirmed SCLC transformation, with no detectable EGFR ex19del or T790M mutations, despite 90% tumour content." (PMID 39972134, 2025). "Importantly, the combination inhibited tumor growth and reduced PD-L1 expression by targeting the EGFR/JAK/STAT3 signaling pathway, demonstrating potential to overcome anti-PD1 therapy resistance." (PMID 40347254, 2025). "Also, the HSP90 inhibitor NXD30001, when combined with radiotherapy, significantly inhibited tumor growth and prolonged the median survival in an EGFR-driven genetically engineered mouse model of GBM." (PMID 39949745, 2025). "Subsequently, an EGFR-expressing B16 lung metastasis tumor model was established in WT mice." (PMID 40122855, 2025). "The EGFR/ERK/MMP pathwayis known to promote tumor progression and metastasis across variouscancer types.37−39 To evaluate the impact of the combination treatmenton these signaling pathways, we analyzed the RNA and protein expressionlevels following the treatment." (PMID 40032551, 2025). "Furthermore, it suppresses tumor-specific EGFR signaling, reduces tumor size, and prolongs the survival of GBM carrier mice." (PMID 40697381, 2025). "Together with the observation that ITGB4 was the only gene of the 5-gene signature also identified as fDEG and component of the invGRN, the current data suggest a central role for ITGB4 in the complex re-programming of tumor cells towards local invasion and in response to EGFR-based treatment." (PMID 40121428, 2025). "Moreover, nanoparticles can be functionalized with ligands targeting specific tumor or stromal markers, such as epidermal growth factor receptor (EGFR), integrins, or FAP, to further improve targeting specificity." (PMID 41179287, 2025). "Therefore, clarifying the mechanism of EGFR-TKI resistance is urgent in the field of tumor pharmacology." (PMID 40703348, 2025). "Therefore, we treated tumor bearing C57Bl/6 mice with encorafenib and the EGFR tyrosine kinase inhibitor gefitinib daily for 3 weeks." (PMID 40264166, 2025). "DARPins binding to such tumor-associated molecular targets, such as human epidermal growth factor receptor 2 (HER2), epithelial cell adhesion molecule (EpCAM), epidermal growth factor receptor (EGFR), vascular endothelial growth factor (VEGF), and hepatocyte growth factor (HGF) have been described." (PMID 40508045, 2025). "A Kirsten Rat Sarcoma Viral Oncogene Homolog (KRAS) exon 2 c.38G>A (p.G13D) mutation was detected in the tumor tissue, whereas mutations in the epidermal growth factor receptor (EGFR) and anaplastic lymphoma kinase (ALK) were negative." (PMID 40630489, 2025). "High expression of EUDAL facilitates sustained phosphorylation of EGFR in hypoxic tumor cells." (PMID 40940319, 2025). "The success of EGFR-targeted ADCs such as MRG003 validates the therapeutic strategy of exploiting highly expressed surface proteins to deliver potent cytotoxic payloads directly to tumor cells." (PMID 41375018, 2025). "Drug-resistant tumors are also able to activate the cMET pathway through increased cMET expression and/or increased cMET ligand expression, which provides an alternative mechanism for tumor cells to bypass the TKI blockade of EGFR and promote cancer cell survival." (PMID 40510353, 2025).
tumor (continued). "Cetuximab is a monoclonal antibody targeting EGFR to block tumor cell growth and proliferation." (PMID 40959565, 2025). "Thus, tumor development can be accompanied by an increased expression of EGFR and phosphorylated EGFRp." (PMID 40732668, 2025). "This, in turn, activates EGFR signaling, which drives tumor growth and angiogenesis." (PMID 40429751, 2025). "EGFR TKIs, by inhibiting EGFR signaling, suppress tumor cell growth and survival." (PMID 40071087, 2025). "Upon ligand binding, EGFR activation induces receptor dimerization and tyrosine autophosphorylation, thereby promoting vascular endothelial growth, tumor neovascularization, cellular proliferation, and enhanced tumor invasiveness." (PMID 41244899, 2025). "However, the MIG6 H393R mutant showed fewer effects compared to the Y395del mutant in various aspects, including enzymatic inhibition of EGFR, cell proliferation, and tumor spheroid growth in organoid models." (PMID 39129344, 2025). "In our data, these also comprised 3 EP tumours without any of the mutations involved in the resistance to the anti‐EGFR treatment." (PMID 40302146, 2025). "In a multivariable analysis including sex, ancestry, smoking, EGFR mutations, KRAS mutations, and mutational signature ID2 in relation to tumor latency, ID2 had the strongest effect size, followed by EGFR mutations and sex, suggesting an independent impact of these factors on LUAD evolution." (PMID 40161734, 2025). "Staining patterns for all selected markers, including CEA, EpCAM, c-MET and EGFR, were predominantly heterogeneous in both tumor and adjacent normal epithelium, exhibiting intra- and inter-sample variations, whereas c-MET staining was mostly homogeneous (intra-sample variation) in normal tissues." (PMID 40563608, 2025). "Moreover,studies targeting the tumor therapy target EGFR showed that kanamycinsignificantly enhanced the silencing effect of LNPs/siEGFR on EGFRmRNA and protein, suggesting its potential application in cancer genetherapy." (PMID 41244463, 2025). "Additionally, although the patient harboured an EGFR L858R mutation, the presence of significant tumour heterogeneity and potential epithelial‐mesenchymal transition (EMT) likely contributed to the poor response to EGFR‐targeted therapy." (PMID 40395487, 2025). "A study on lung cancer revealed that TAMs promote the migration and invasion of tumor cells through the secretion of cytokines such as IL-6 and IL-8 and simultaneously increase the resistance of tumor cells to EGFR inhibitors, reducing the efficacy of chemotherapeutic drugs." (PMID 40850976, 2025). "A dedicated study involving exclusively RAS/BRAF wild-type patients would be necessary to establish whether anti-EGFR therapy is superior to anti-VEGF therapy in terms of inducing tumor fibrosis ≥40%." (PMID 40507350, 2025). "The upregulation of EGFR and/or AREG upon entinostat treatment suggests that the tumor cells may become then more sensitive towards EGFR inhibition." (PMID 39864337, 2025). "Meanwhile, genomic profiling of tumor tissue via next-generation sequencing (NGS) panels identifies driver mutations (e.g., EGFR, BRAF) and gene fusions (e.g., ALK, ROS1), enabling selection of small-molecule inhibitors that specifically block oncogenic signaling." (PMID 41301080, 2025). "However, in August 2018, EGFR-TKI was discontinued due to the recurrence of the tumor in the left lung." (PMID 41001033, 2025). "Additionally, EGFR amplifications and mutations drive MAPK and PI3K/Akt hyperactivation, promoting tumor proliferation and resistance to apoptosis." (PMID 40076502, 2025). "However, clinical trials targeting specific antigens like EGFR or CD44v6 have shown promise in improving immune cell recognition, transitioning the tumor into a hot immune environment." (PMID 40281554, 2025). "Thus, we demonstrated that 10k and 10l are promising FAK inhibitors in NSCLC that resensitize EGFR-TK-resistant tumor to Afatinib or Osimertinib treatment." (PMID 41281943, 2025).
tumor (continued). "Specific depletion of RNA in OSCC sEVs significantly impaired their pro-angiogenesis ability, indicating that enhanced loading of sRNA may be the key mechanism by which tumor cells with elevated EGFR expression promote angiogenesis through sEVs." (PMID 39816681, 2025). "Optimisation of treatments, therefore, firstly to select the patients who are intrinsically sensitive to EGFR inhibitors and, secondly, to delay the outgrowth of drug-resistant tumours during EGFR targeted therapy, could provide better treatment options." (PMID 40615716, 2025). "It was found that EGFR mutations were directly associated with PD-L1 upregulation in NSCLC patients, which could lead to increased risk of tumor immune escape." (PMID 39852160, 2025). "Notably, in patient 5, a tumor rebiopsy revealed a significant increase in CTNNB1 mutation frequency (0.4%-30.0%), alongside an increase in EGFR allele frequency (27/28% to 62/62%), correlating with a higher tumor cell content (40% v 70% at rebiopsy)." (PMID 40768678, 2025). "This implied that FH-EB02 primarily bound to tumor cells and blocked EGFR signaling through its interaction with B7H3, providing a large therapeutic window and thereby further reducing the binding of the bsAb to EGFR targets in normal tissues and mitigating side effects." (PMID 41291854, 2025). "Besides mAbs directed against tumor-associated antigens (e.g., CD20, EGFR, HER-2), innovative molecules, such as bi- or tri-specific antibodies or other NK cell engagers (NKCE), have been recently designed." (PMID 39958331, 2025). "The heterogeneity was not linked to a specific EGFR mutation, tumor type, or the tobacco smoking history of the patient." (PMID 39747003, 2025). "When administered intraperitoneally (IP) in nude mice bearing human EGFR tumor xenografts, disruptin promoted EGFR degradation without causing damage to host cells." (PMID 40428099, 2025). "Although we were not able to assess tumour mutations, an EGFR gene mutation has been associated with adenocarcinoma in females." (PMID 40650926, 2025). "Finally, cell-derived xenograft (CDX) models were generated by subcutaneously implanting pre-treated PC9 or HCC827 cells into BALB/c nude mice to verify the impact of EGFR-TKI resistance and ZEB2 on tumor-associated macrophage (TAM) polarization in vivo." (PMID 40510028, 2025). "Our data support the role of ctDNA in capturing ongoing tumor evolution, suggesting that specific mutations, including rare variants in KRAS, EGFR, and PIK3CA, may contribute to resistance and progression." (PMID 40652269, 2025). "SREBP is frequently upregulated in various cancers, potentially through tumor cell-expressed Programmed Cell Death Ligand 1, which activates the EGFR/integrin subunit β4/SREBP1c signaling axis, thereby driving lipid metabolic reprogramming and supporting tumor progression." (PMID 41345744, 2025). "In line with this, we found low expression of EGFR on patient tumor cells, which could explain the inefficacy of IgG mAbs in clinical trials for PDAC." (PMID 40358156, 2025). "Although the advent of epidermal growth factor receptor (EGFR) tyrosine kinase inhibitors (TKIs) has markedly improved outcomes for patients with EGFR-mutant tumors, resistance development, tumor heterogeneity, and immune escape continue to hinder long-term efficacy." (PMID 41401147, 2025). "This riddle may be explained by the fact that oncogenic EGFR or Ras activate an array of tumor-promoting pathways in addition to the Erk cascade, making their oncogenicity more powerful and more resistant to cellular protective systems." (PMID 40394416, 2025). "Tyrosine kinase receptor-blocking antibodies, like cetuximab for EGFR, have a dual mechanism of action: the variable regions block receptor–ligand interactions to induce intrinsic effects on tumor cells, and the Fc binds Fcγ receptors in leukocytes that induce cellular immunity." (PMID 41219228, 2025).
tumor (continued). "Notably, though resistant to chemotherapeutics, Scissor+ tumor cells were responsive to targeted therapies, especially EGFR inhibitors (afatinib, icotinib, and osimertinib)." (PMID 40098972, 2025). "Cancer cells sensitive to EGFR-TKIs may retain their responsiveness to the targeted drug during tumor progression." (PMID 40191716, 2025). "For instance, co-administration with EGFR-targeted TKIs or immune checkpoint inhibitors may yield additive or synergistic tumor control by simultaneously targeting CHRM3-driven proliferation and enhancing apoptotic or immune-mediated clearance." (PMID 40718823, 2025). "As a result, combining EGFR-TKIs with immune checkpoint inhibitors, such as PD-1/PD-L1 inhibitors, holds potential for remodeling the immune microenvironment and strengthening the anti-tumor immune response." (PMID 40003951, 2025). "In the context of CRC, we demonstrated that hydrogel scaffolds implanted directly at the tumor site could sustainably inhibit EGFR internalization, increase cetuximab binding to tumor cells, and enhance cetuximab‐mediated ADCC activity." (PMID 39560161, 2025). "Further investigations revealed that ANO1 amplification and overexpression are significantly correlated with tumor grade and poor prognosis, promoting tumor proliferation through the epidermal growth factor receptor (EGFR) and calmodulin-dependent protein kinase II (CAMKII) signaling pathways." (PMID 40356890, 2025). "Notably, conventional CAR-T cells preferentially attacked tumor cells with high and medium EGFR, whereas EGFR-BBζ + CD2 CAR-T cells exhibited a markedly reduced bias." (PMID 40615696, 2025). "Similarly, tumor‐derived exosomal EGFR and phospho‐EGFR fall during anti‐EGFR (cetuximab) therapy, suggesting EV‐EGFR can monitor therapeutic response." (PMID 41050664, 2025). "Finally, considering reports suggesting that the primary tumor location affects the efficacy of anti-EGFR antibodies, the relationship between primary tumor location and treatment efficacy was evaluated." (PMID 39941768, 2025). "Taken together, our data on all EGFR cohorts emphasize the need for the development of treatments focusing on long-term tumor control, e.g., by immune-combination strategies, which might make EGFR-tumor cells more “visible” to the immune system." (PMID 40227775, 2025). "Based on the characteristicpeaks of CyNAMLA-381, Cy7LA, and Cy7.5LA (523, 503, and 586 cm–1), the images at the tumor sites showed high SERSintensities for anti-EGFR antibody conjugated CyNAMLA-381 and Cy7LAnanotags, but low intensities for anti-HER2 antibody conjugated Cy7.5LAnanotags." (PMID 40687502, 2025). "There are a number of ways in which EGFR can be dysregulated in tumor cells." (PMID 39796751, 2025). "Furthermore, different tumor cells’ EGFR expression can result in less effective targeting, and the high cost of producing customized siRNAs prevents widespread clinical use." (PMID 40805153, 2025). "In addition, the interaction of EGFR with other RTKs broadens the available downstream pathways allowing tumor cells to circumvent EGFR inhibition." (PMID 40003864, 2025). "Moreover, we show that these EGFR‐high tumour cells overexpressed LGALS3, CD59, laminins (LAMB1 and LAMB3), PROS1 and so on that induced LAG3 and CD44 expression in the associated CD8+ T cells featuring an exhaustion state." (PMID 40621643, 2025). "Additionally, previous studies have shown that EGFR and TLRs are functionally involved in cancer development and progression by modulating inflammation, tumor cell behavior, and immune responses." (PMID 41419456, 2025). "This stage may be responsible for the very slow degradation of EGFR and specific signaling in undifferentiated normal MSCs compared to tumor-derived cells." (PMID 41155514, 2025). "Furthermore, the anti-tumor efficacy of EGFR and HER2 FolTAC-dual v1.0 was evaluated in an in vivo model." (PMID 41038820, 2025).
tumor (continued). "To determine whether ErbB signaling drives the increased tumorigenesis observed in Tpl2−/− mice, we evaluated the effects of EGFR or HER2 inhibition on tumor development and cSCC progression in our model." (PMID 41154417, 2025). "Notably, while Dio upregulates EGFR expression via the Notch1/Jagged1 pathway in liver regeneration models, it exhibits suppressive effects on EGFR activity in tumor contexts." (PMID 40391080, 2025). "Given the critical role of TAK1, NF-κB, EGFR and Akt pathways in therapy resistance and tumor progression, agents like DHC that inhibit these pathways could provide a therapeutic advantage, especially in cancers that are refractory to conventional treatments." (PMID 40507823, 2025). "Furthermore, these complexes exhibit notable tumor‐specific accumulation, significantly enhancing the active targeting of EGFR‐overexpressing tumors in vivo." (PMID 40666030, 2025). "Additionally, depletion of PCBP2 impaired the EGFR-driven tumor angiogenesis by inhibiting the secretion of pro-angiogenic miRNAs through sEVs." (PMID 39816681, 2025). "Moreover, tumor-associated macrophages (TAMs) in EGFR-mutated NSCLC exhibit an immunosuppressive M2 phenotype, secreting factors like IL-10 and VEGF, which promote tumor progression and immune evasion." (PMID 40733125, 2025). "Based on these insights, we reasonably infer that Hh pathway inhibitors and EGFR-targeting antibodies may act synergistically, with their combination potentially delaying or even preventing tumor recurrence." (PMID 41214390, 2025). "The association of the AR status with clinicopathological factors (age, stage, tumor diameter, lymph node invasion, metastatic spread, Ki-67 score, EGFR score, and cytokeratin 5/6 score) and the disease outcome (disease-free survival—DFS—and overall survival—OS) was investigated." (PMID 40150035, 2025). "An EGFR inhibitor is added if the tumor is wild-type for KRAS, NRAS, and BRAF." (PMID 40004690, 2025). "In addition, they showed that blockade of the HB-EGF–EGFR pathway using EGFR inhibitors (such as erlotinib) reduced angiogenesis and tumor growth in in vitro and in vivo models of MM." (PMID 40115011, 2025). "In particular, interleukin 6 expression has been associated with worse outcomes in patients with NSCLC treated with EGFR-TKIs, which may induce tumor refractoriness to EGFR-TKIs via JAK–STAT3 signaling activation or suppression of anti-tumor immune responses." (PMID 40136696, 2025). "Notably, the combination treatment significantly inhibits tumor growth by targeting the EGFR/JAK/STAT3 signaling pathway, contributing to the reduction of PD-L1 expression associated with immune evasion." (PMID 40347254, 2025). "GOLM1 affected EGFR trafficking and promoted tumour progression." (PMID 40293576, 2025). "Interestingly, in this model, Toll signaling is suggested to accelerate tumor growth through positive regulation of Epidermal growth factor receptor (EGFR) levels, although the mechanism behind this is still unclear." (PMID 40143968, 2025). "Notably, the combination of panitumumab (an EGFR monoclonal antibody) with an ICI has a more substantial inhibitory effect on tumor growth than ICI alone." (PMID 40560045, 2025). "For instance, combining EGFR inhibitors with immune checkpoint inhibitors could provide synergistic effects by simultaneously targeting tumor growth and enhancing the immune response." (PMID 40336633, 2025). "While EGFR mutations typically arise in non-smokers and are correlated with non-inflamed tumor microenvironment, KRAS mutations are associated with tobacco smoking, high mutational burden, and immunologically more active tumors." (PMID 40524071, 2025). "In addition to CCND1, rearrangements involving genes such as PIK3CA and EGFR are also implicated in OSCC pathophysiology, contributing to tumor progression and reduced therapeutic efficacy, thereby representing potential targets for novel treatment strategies." (PMID 40427514, 2025).